HSPD1 (heat shock protein family D (Hsp60) member 1)
Diseases named in the same sentence as HSPD1 in open-access papers (continued):
Sharing a sentence is not in itself a finding about the gene and the disease.
type 2 diabetes (3 papers, 2016 to 2024). "In fact, in a murine model of type II diabetes mellitus, downregulation of mitochondrial HSPD1 caused hypothalamic insulin resistance and mitochondrial dysfunction consequent to disruption of leptin signaling." (PMID 27125468, 2016).
viral infection (3 papers, 2017 to 2022). "Together, these results suggest that ATAD3A and HSPD1 have the ability to promote BmNPV DNA accumulation in viral infection cells." (PMID 28393927, 2017).
cardiomyopathies (2 papers, 2021 to 2022). "Although this is the first study demonstrating Hsp mutations in PPCM, genetic variation in HSPB5, HSPB7 and HSPD1 has been reported in other cardiomyopathies." (PMID 33467574, 2021). "A recent study has linked HSPD1 mutations with cardiomyopathy when the mutation p.Thr320Ala was described in a Japanese family with DCM and arrhythmia." (PMID 33467574, 2021). "Other HSPD1 mutations may need to be reported in additional cardiomyopathy families before its role in disease pathogenesis is clarified." (PMID 33467574, 2021). "Although the mechanisms whereby HSPD1 may contribute to cardiomyopathy are unclear, the authors demonstrated that a similar mutation in zebrafish resulted in a DCM phenotype with mitochondrial damage and increased levels of reactive oxygen species, as well as a reduced tolerance to exercise stress." (PMID 33467574, 2021). "Genes important in these processes and that are associated with cardiomyopathy include DNAJC19, MAGMAS, TIMM50, MIPEP, XPNPEP3, HTRA2, CLPB and HSPD1." (PMID 35328774, 2022). "To date, disorders resulting from mutations in the HSPD1 gene have not been associated with cardiomyopathy in humans." (PMID 35328774, 2022).
Cognitive impairment (2 papers, 2023). Abnormal cognition is characterized by deficits in thinking, reasoning, or remembering. "Seven differentially expressed autoantibodies were recognised as cognitive impairment-related, including HSPD1, CDK19, TKT, BRSK2, NRAS, LMNA, and CAMK2A." (PMID 38107644, 2023).
hereditary spastic paraplegia 13 (2 papers, 2016 to 2020). Any hereditary spastic paraplegia in which the cause of the disease is a mutation in the HSPD1 gene. "Mutations of the HSPD1 gene are associated with spastic paraplegia 13, AD (SPG13, MIM 605280), a neurodegenerative disorder characterized by a slow, progressive weakness and spasticity of the lower limbs, whose rate of progression and clinical severity can vary." (PMID 26907355, 2016).
liver cancer (2 papers, 2020 to 2025). An epithelial or non-epithelial malignant neoplasm that arises from the liver. "Among them, the top three proteins are mitochondrial 60 kDa heat shock protein (HSPD1), trifunctional enzyme subunit alpha (HADHA), and carbamoyl-phosphate synthase (CPS1), which may be involved in the response to HBV-associated liver cancer progression." (PMID 40519923, 2025).
liver fibrosis (2 papers, 2016 to 2020). "Hspd1 and Hspb1, two proteins uniquely identified by 2D-PAGE upon exposure of milkfish to lethal hypothermal environment, might play a critical role in decreasing intrinsic apoptotic effects and liver fibrosis." (PMID 27657931, 2016).
lymph node metastasis (2 papers, 2019 to 2022). "HSPD1 was established as a protein biomarker for metastatic BC related to lymph node metastasis and regional metastasis." (PMID 36500393, 2022).
meningitis (2 papers, 2021 to 2022). A disorder characterized by acute inflammation of the meninges of the brain and/or spinal cord. "This study provides a greater understanding of the pathogenic role of HSPD1 in S. suis-serovar-2-induced meningitis and forms the basis for new therapeutic strategies to treat bacterial meningitis." (PMID 35805155, 2022). "We had previously found that S. suis serovar 2 Eno, as a virulence factor involving meningitis, promotes HSPD1 expression in PBMECs by targeting RPSA, which in turn induced apoptosis, hurting the BBB integrality." (PMID 35805155, 2022). "Fortunately, HSPD1 inhibitors or regulators are confirmed to be able to modify and regulate HSPD1 expression and functions and, for this reason, their use can be switched from cancer therapy to anti-infective therapy, or treatment for meningitis." (PMID 35805155, 2022). "Future research should focus on revealing the mechanism of action of HSPD1/ACTB inhibitors, which have great potential for treating meningitis if they can be ensured to be safe in treated animals and humans." (PMID 35805155, 2022). "This study reveals novel functions for the host-interactional molecules RPSA and HSPD1 in BBB integrity, and provides insight for new therapeutic strategies in meningitis." (PMID 33618766, 2021).
neuroblastoma (2 papers, 2021 to 2023). Neuroblastoma (NB) is the most common solid, extracranial childhood tumor. "PDIA3 identified following from DAT of MPN was found to be directly interacting with PRDX1 (found in both DAT of MPN and DMT of neuroblastoma cells), ACTB (found in DAT of MPN and both in DAT and DMT of neuroblastoma cells), and HSPD1." (PMID 34394070, 2021).
oral cancer (2 papers, 2019 to 2022). "Through data analysis with The Cancer Genome Atlas (TCGA), we found the association of HSPD1 gene expression with tumorigenesis and poor prognosis in oral cancer patients." (PMID 31222140, 2019). "In the study, we reported the following findings: First, we found HSPD1 gene expression was associated with both tumorigenesis and poor prognosis in oral cancer patients from TCGA database." (PMID 31222140, 2019). "Analysis with another independent cohort from TCGA database also showed that oral cancer patients with co-expression level of high HSPD1/low E-cadherin had poor OS compared to those with co-expression level of low HSPD1/high E-cadherin." (PMID 31222140, 2019). "To examine the clinical significance of HSPD1 in oral cancer, we analyzed gene expression levels of HSPD1 and several reported HSPs between 30 normal tissues and 315 tumor tissues in oral cancer patients with TCGA dataset." (PMID 31222140, 2019). "At the same time, they found that silencing HSPD1 could suppress metastasis of oral carcinoma via upregulation of E-cadherin expression." (PMID 35342421, 2022). "Notably, survival rate of oral cancer patients with co-expression level of low HSPD1/low E-cadherin is higher than those with co-expression level of high HSPD1/high E-cadherin from TGCA cohort, which is opposite to the findings in our cohort study." (PMID 31222140, 2019). "However, the role of HSPD1 in oral cancer, especially in BMSCC, is still unknown." (PMID 31222140, 2019). "However, the clinical significance and molecular mechanism of HSPD1 in oral cancer is still not clear, particular in BMSCC." (PMID 31222140, 2019). "However, the clinical role of HSPD1 and its molecular mechanisms in cancer metastasis is not clear in oral cancer." (PMID 31222140, 2019).
psoriasis (2 papers, 2021 to 2024). An autoimmune condition characterized by red, well-delineated plaques with silvery scales that are usually on the extensor surfaces and scalp. "Using ELISA, we analyzed the expression of KRT19 and HSPD1 in lesional skin as well as the PBMC of qPCR/ELISA psoriasis patients and healthy volunteers." (PMID 34575702, 2021).
pulmonary disease (2 papers, 2021 to 2022). "Differential expression of HSPD1, involved in mitochondrial biogenesis, was noted in patients suffering from pulmonary diseases compared with normal controls." (PMID 34366885, 2021).
allergic asthma (1 paper, 2021). A asthma with a basis in a pathological type I hypersensitivity reaction. "HSPD1 has been found to be involved in the alveolar macrophages immune functions in relation to allergic asthma." (PMID 34394070, 2021).
Alzheimer disease (1 paper, 2023). A progressive, neurodegenerative disease characterized by loss of function and death of nerve cells in several areas of the brain leading to loss of cognitive function such as memory and language. "According to the disease alliance terms, ENO1, CASP6, HSPD1, and CASP3 are associated with Alzheimer’s disease." (PMID 38107644, 2023).
anemia (1 paper, 2019). A reduction in the number of red blood cells, the amount of hemoglobin, and/or the volume of packed red blood cells. "In this study, we used Tie2-Cre to deactivate the Hspd1 gene in both hematopoietic and vascular endothelial cells, and found that Tie2-Cre+Hspd1f/f (HSP60CKO) mice were embryonic lethal between the embryonic day 10.5 (E10.5) and E11.5, exhibiting growth retardation, anemia, and vascular defects." (PMID 31601784, 2019).
atrial fibrillation (1 paper, 2025). A disorder characterized by an electrocardiographic finding of a supraventricular arrhythmia characterized by the replacement of consistent P waves by rapid oscillations or fibrillatory waves that vary in size, shape and timing and are accompanied by an irregular ventricular response. "The research found that serum HSP levels (including HSPB1, HSPA1, HSPB7, and HSPD1) lacked clinical value in predicting postoperative atrial fibrillation (PoAF)." (PMID 40786071, 2025).
autosomal dominant spastic paraplegia (1 paper, 2025). "Pathogenic mutation of HSPD1 contributes to the onset of two distinct mitochondrial diseases: autosomal dominant spastic paraplegia 13 (SPG13, MIM #605280) and autosomal recessive hypomyelinating leukodystrophy 4 (HLD4, MIM #612233)." (PMID 40857737, 2025).
cholelithiasis (1 paper, 2012). The presence of crystallized deposits forming in the gallbladder or biliary tree, primarily composed of cholesterol, bilirubin, and bile. "PDIA3 and HSPD1 could be detected in several cholelithiasis patients; however, the average expression levels of PDIA3 and HSPD1 in crude bile from CC patients was significantly higher." (PMID 23118872, 2012).
chronic kidney disease (1 paper, 2017). Impairment of the renal function secondary to chronic kidney damage persisting for three or more months. "The inverse relationship between miR-382 expression and renal expression of HSPD1 also exists in the obstructed kidneys of UUO mice as well as in patients with chronic kidney disease." (PMID 28680529, 2017).
clear cell renal cell carcinoma (1 paper, 2023). "HSP60 is decreased in clear cell renal cell carcinoma (ccRCC) compared to associated pericarcinous tissues and HSPD1 knockdown promotes ccRCC progression." (PMID 37087461, 2023).
cryptorchidism (1 paper, 2018). The failure of one or both testes of a male fetus to descend from the abdomen into the scrotum during the late part of pregnancy. "Hspe1 showed > 3.0 fold up-regulation in heat stressed round spermatids and its companion protein Hspd1 was up-regulated (3.2 fold) after 120 h of cryptorchidism." (PMID 29859541, 2018).
dilated cardiomyopathy (1 paper, 2019). Cardiomyopathy which is characterized by dilation and contractile dysfunction of the left and right ventricles. "Impairment of HSPD1-mediated anti-stress response has been reported in dilated cardiomyopathy (DCM) which progressed to end stage heart failure." (PMID 31323898, 2019).
hilar cholangiocarcinoma (1 paper, 2012). A cholangiocarcinoma that arises from the junction, or adjacent to the junction, of the right and left hepatic ducts. "Intense PGAM-1, HSPD1, PDIA3 and SSP411 cytoplasmic immunoreactivity was observed in both hilar cholangiocarcinoma and intrahepatic cholangiocarcinoma." (PMID 23118872, 2012).
IgA nephropathy (1 paper, 2017). "Our clinical data showed that upregulation of miR-382/3-NT and downregulation of HSPD1/Trx were also observed in IgA nephropathy patients with renal interstitial fibrosis." (PMID 28680529, 2017).
ischemic stroke (1 paper, 2024). A stroke disorder caused by obstruction of blood flow to the brain, due to thrombotic (local blood clot formation) or embolic (due to a blood clot or other material traveling from another site) event. "Interestingly, in our previous study, we observed an association between variations in HSPD1, which encodes the Hsp60 family member, and the risk of ischemic stroke, but this association was found exclusively in smokers." (PMID 39723236, 2024).
kidney cancer (1 paper, 2023). Primary or metastatic malignant neoplasm involving the kidney. "In kidney cancer cell lines, high HSPD1 expression was significantly associated with sensitivity to 30% of DNA rep." (PMID 37508418, 2023).
large cell lymphoma (1 paper, 2019). "HSPD1 encodes a heat-shock family protein chaperone that exhibits elevated expression in Hodgkin’s and large cell lymphoma and is involved in the B and T cell immune response." (PMID 30857150, 2019).
liposarcoma (1 paper, 2013). A usually painless malignant tumor that arises from adipose tissue. "For instance, we found a HSPD1-PNPLA4 chRNA in both KPL-4 and SK-BR-3 libraries: PNPLA4 (GS2) is highly expressed in human SW872 liposarcoma cells, while HSPD1, the heat shock protein Hsp60, shows a broad antiapoptotic function in cancer." (PMID 23537109, 2013).
lung squamous cell carcinoma (1 paper, 2021). "The mRNA expression levels of TRAP1 and HSPD1 were increased in lung squamous cell carcinoma." (PMID 34712697, 2021).
lymphopenia (1 paper, 2025). Reduction in the number of lymphocytes. "What's more, the upregulation of pro-apoptotic genes HSPD1 and S100A917, 36, 37, the downregulation of anti-apoptotic gene HSPA816, 17, and the activation of apoptosis all suggest the pathological processes underlying lymphopenia following heatstroke." (PMID 40084252, 2025).
Macrocephaly (1 paper, 2014). Occipitofrontal (head) circumference greater than 97th centile compared to appropriate, age matched, sex-matched normal standards. "Participant 178 is a 14-month-old male with macrocephaly and two ROHs on chromosomes 2 and 11 involving the HSPD1, PACS1, NDUFV1, and NDUFS8 genes that may play a role in psychomotor delay, hypotonia, and atypical development." (PMID 25400949, 2014).
mental disorder (1 paper, 2025). A disease that has its basis in the disruption of mental process. "Here, both C1qbp and Hspd1 fit this profile, which raises the possibility that these proteins are a link between the immune system and this mental disorder." (PMID 40299488, 2025).
muscle tumors (1 paper, 2023). "In addition, 25 DPs are related to muscle tumors; 8 DPs (APOE, FCER1A, FCER2, GSK3B, HSPD1, IL6R, MMP7, and RARRES2) are linked to proliferation of muscle cells." (PMID 36918772, 2023).
oral cavity cancer (1 paper, 2019). A primary or metastatic malignant neoplasm involving the oral cavity. "Because BMSCC is the most common oral cavity cancer, we further investigated the clinical role of HSPD1 in BMSCC patients." (PMID 31222140, 2019).
prostate adenocarcinoma (1 paper, 2026). "Subsequent transcriptomic analysis of TCGA-PRAD datasets identified > 6000 mRNAs significantly upregulated in prostate adenocarcinoma tissues, with HSPD1 (encoding HSP60) showing particularly pronounced overexpression." (PMID 41522350, 2026).
renal fibrosis (1 paper, 2017). A final common manifestation of a wide variety of chronic kidney diseases characterized by glomerulosclerosis and tubulointerstitial fibrosis. "The antioxidative capacity of renal tissue declined when HSPD1 expression was downregulated, which suggested that excessive oxidative stress may be an important mechanism whereby miR-382 participates in renal fibrosis." (PMID 28680529, 2017).
steatosis (1 paper, 2021). Increased lipid within the cytoplasm of cells. "It revealed that expression levels of HSPD1 mRNA (p = 0.007), MMP14 mRNA (p = 0.015), miR-6881-5p miRNA (p = 0.046) and lncRNA lnc-SPARCL1-1:2 (p = 0.006) were independent predictors of NASH, and NAFLD scoring steatosis grading and fibrosis scoring (p = 0.04)." (PMID 34572434, 2021). "We concluded that HSPD1/MMP14/ITGB1/miR-6881-5P/Lnc-SPARCL1-1:2 panel expression has a potential in the diagnosis of NASH, and also in differentiation between NAFLD without steatosis, NAFLD with simple steatosis and NASH." (PMID 34572434, 2021). "In our study, we found upregulation in the expression of HSPD1 mRNA with discriminative cutoff values between NASH cases and the healthy control group that could also discriminate between NAFLD without steatosis, NAFLD with simple steatosis and NASH cases." (PMID 34572434, 2021).
Stroke (1 paper, 2025). Sudden impairment of blood flow to a part of the brain due to occlusion or rupture of an artery to the brain. "The increase in the HSPD1 (HSP60) gene expression was found in the stroke-affected hemisphere after 7 days when compared to in the contralateral hemisphere (p < 0.05) and compared to the 6 h and 3 d group (p < 0.05)." (PMID 40332314, 2025).
sudden infant death syndrome (1 paper, 2016). Unexpected death in infancy which remains unexplained following autopsy, review of the medical history, and investigation of the death circumstances and death scene. "Studies have shown increased frequency of the pathogenic variant of the HSPD1 single-nucleotide variant in a subgroup of sudden infant death syndrome (SIDS) patients." (PMID 27803687, 2016).
temporal lobe epilepsy (1 paper, 2019). A localization-related (focal) form of epilepsy characterized by recurrent seizures that arise from foci within the temporal lobe, most commonly from its mesial aspect. "HSPD1 levels in the serum are increased in both temporal lobe epilepsy patients and in the animal model of the disease in response to seizures, suggesting that plasma HSPD1 can be used as a biomarker reflecting neuronal cell death." (PMID 31507418, 2019).
infection (90 papers, 2006 to 2026). The state of being infected such as from the introduction of a foreign agent such as serum, vaccine, antigenic substance or organism. "The survival rates of SS2-infected mice with knockdown of RPSA (50%) and HSPD1 (40%) were significantly increased at 36 h post-infection (shControl group, 0%)." (PMID 33618766, 2021). "Of these genes, only the upregulation of Hspa1a and Il1a was maintained 24 h after infection, and the expression of the heat shock protein 1 (Hspd1) gene was upregulated." (PMID 30555476, 2018). "Stable cell lines of ATAD3A and HSPD1 significantly increased BmNPV multiplication compared with pIZ-V5/His cell lines at different time points post infection." (PMID 28393927, 2017). "All subjects acquire adaptive immunity against bacterial HSP60/65 by infection and, because there is a high degree of homology between mammalian and bacterial HSPD1/HSP60, this can trigger an immune cross-reaction against human HSPD1/HSP60." (PMID 29240668, 2017). "Changes in heat shock protein transcript levels after infection of fibroblasts with S. aureus and treatment with wIRA were observed for HSPD1 as a slight increase and with heating w/o wIRA for HSPA1A as significant enhancement (p < 0.05) compared to infected cells." (PMID 34944618, 2021). "Furthermore, to examine whether ATAD3A and HSPD1 were involved in BmNPV infection, we analyzed the changes of BmNPV DNA replication." (PMID 28393927, 2017). "We found that, upon infection with S. aureus, ACO2 KD further increased the expression of HSPD1, HSPA9, and CLIPP, three of four selected targets of ATF5, a key mediator of the UPRmt and the mammalian ortholog of C. elegans ATFS-1, in HeLa cells." (PMID 37349299, 2023). "Western blot analyses showed that BmNPV VP39 protein increased after infection with stable cell lines of ATAD3A and HSPD1 at different time-points." (PMID 28393927, 2017). "Statistical analysis results also showed that the average number of EGFP+ positive cells increased significantly after BmNPV infection with stable cell lines of ATAD3A and HSPD1 during specific periods of time." (PMID 28393927, 2017). "The incorporation of HSPD1 into the virion could ensure the stability and folding of the HIV integrase in preparation for the upcoming infection, especially when the cellular level of heat shock proteins is decreased." (PMID 34835333, 2021).